STAT3 (signal transducer and activator of transcription 3)
Diseases named in the same sentence as STAT3 in open-access papers (continued):
Sharing a sentence is not in itself a finding about the gene and the disease.
cancer (continued). "As suggested by both our transcriptome and protein analyses, the link between TLR9/NF-κB and STAT3 signaling likely relies on IL-6 secretion by cancer cells." (PMID 26046794, 2015). "When compared with the control cells as well, the indicated cixutumumab-treated or IGF-1R-silenced cancer cells showed increased levels of STAT3 phosphorylation, which was established by western blotting." (PMID 26465273, 2015). "Persistently activated STAT3 in cancer cells also leads to suppression of the anti-oncogenic cytokines interferons Type I (α and β) and Type II (γ)." (PMID 25685909, 2015). "Among the STATs family members, STAT3 is a prominent molecular hub connecting multiple vital molecular pathways involved in cancer progression." (PMID 26024373, 2015). "The ruxolitinib-treated xenografts also had markedly increased numbers of Ki-67+ cancer cells accompanied by a decrease in STAT3 and p14ARF expression." (PMID 26198641, 2015). "p-STAT3 expression was localized in the nucleus of the cancer cells and scattered widely in the cancer nests." (PMID 25761055, 2015). "STAT3 signaling plays a major role in the intrinsic pathway of cancer inflammation and participates in oncogenesis through upregulation of genes involved in proliferation, antiapoptosis and angiogenesis." (PMID 26551008, 2015). "Among the cytokines linked to inflammation-associated cancer, IL-6 appears to drive oncogenesis via downstream activation of the JAK/STAT3 signaling pathway." (PMID 25789077, 2015). "Previous reports have demonstrated that curcumin can abrogate constitutive phosphorylation of STAT3 in various cancer cell lines." (PMID 25961579, 2015). "In some hematopoietic disorders and cancers,overexpression and activation of STAT3 result in high proliferation, suppression ofcell differentiation and inhibition of cell maturation." (PMID 26464811, 2015). "The cancer-related inflammation pathway- signal transducer and activator of transition 3 (STAT3) signaling pathway has been reported to play critical role in its initiation and progression, while the way mediated its hyperactivation remains elusive so far." (PMID 25928665, 2015). "Although STAT3 has been proven to regulate CSCs in some cancers, its involvement through Btk signaling in ovarian cancer remains unproven." (PMID 26036311, 2015). "STAT3 is considered as an ideal molecular target of cancer therapy because this target plays a pivotal role in tumorigenesis and cancer cell biology." (PMID 26631279, 2015). "Taken together, all these data indicate that STAT3 is involved in Lycorine induced inhibition to PCa cells and the anti-cancer effects of Lycorine are dependent on STAT3 expression." (PMID 25915156, 2015). "As such, STAT3 activation is critically involved in the processes of cancer initiation, progression and maintenance and elevated levels of active STAT3 are associated with poor prognosis in a host of hematopoietic and non-hematologic malignancies." (PMID 26430964, 2015). "As such, it represents a potentially relevant target for therapeutic intervention in many cancers and several inhibitors of STAT3 are currently under investigation." (PMID 26272737, 2015). "On the other hand, ROS can stimulate the JAK2/STAT3 pathway through the induction of a positive ROS/IL-6/JAK2/STAT3 feedback during starvation-induced autophagy of cancer cells." (PMID 26106584, 2015). "The Stat3-mediated transcription of several antiapoptotic genes contributes to the survival of cancer cells." (PMID 26697428, 2015).
cancer (continued). "There is now substantial data supporting the role of STAT proteins in cancer biology, including the observation that constitutive activation of STAT3 is present in a variety of human malignancies." (PMID 26272737, 2015). "Previous studies showed that PTL targeted NF-kB, Stat3, Bcl-2, reactive oxidative species (ROS) in cancer cells." (PMID 25658946, 2015). "In the high IL-6 expression group, IL-6 receptor (IL-6R), phospho-signal tranducer and activator of transcription 3 (p-STAT3) were also detected in almost all the cancer cells." (PMID 25761055, 2015). "Oxidative stress in the stroma, which is generally caused by cancer cells at the onset of their synergy, promotes CAF transformation and HIF1, NFkB, JNK, STAT3 and TGFβ activation in the stromal compartment." (PMID 25915429, 2015). "It possesses anti-cancer activities through blocking the transcription factor STAT3 and by inducing reactive oxygen species (ROS) in cancer, but not normal cells." (PMID 26645674, 2015). "Overall, our study suggested that caged xanthones exhibited strong anticancer activity on a panel of cancer cell lines, especially those whose survival and growth are dependent on constitutively active STAT3 signaling." (PMID 26090459, 2015). "An improved understanding of the complex roles of STAT3 in cancer is required to achieve optimal therapeutic effects." (PMID 26631279, 2015). "Btk silencing effectively reduced the expression of the Janus kinase 2 (JAK2)/STAT3 pathway, which in turn suppressed the survival of cancer cells through Sox-2 and BCL-XL genes and, finally, restored responsiveness to cisplatin." (PMID 26036311, 2015). "There is a well-established link between the p38, NFkB, PI3K and STAT3 pathways, inflammation, resistance to apoptosis and cancer." (PMID 26220208, 2015). "STAT3 always play a critical role in oncogenic signaling in the carcinogenesis and progression of several cancers." (PMID 25928665, 2015). "Mutations were found most frequently in 3 genes, STAT3, BCOR, and MLL2 (which were present in 9, 7, and 6 cancer samples, respectively), whereas there were only 2 cases of JAK3 mutation." (PMID 25980440, 2015). "NFκB is constitutively active in most cancers and exhibits extensive networking with several cancer signaling pathways, including STAT3." (PMID 25868979, 2015). "Silencing IGF-2 or STAT3 expression in cancer cells or IGF-2R or CXCL8 expression in stromal cells significantly inhibits the cancer–stroma communication and vascular endothelial cells' angiogenic activities." (PMID 26465273, 2015). "Although the association of Stat3 with individual complexes of the ETC has been previous described in heart and cancer cells, here we show for the first time the presence of Stat3 in the ETC SCs in CD4 cells." (PMID 25974216, 2015). "By blocking phosphorylation of STAT-1 and STAT-3 as well as NFκB signaling, curcumin had bi-functional effects on cancer: promotion of apoptosis but blockade of the principal anti-oncogenic cytokine IFN-γ (Type II interferon)." (PMID 25685909, 2015). "Because of the importance of STAT3 in regulating cell growth and survival, the STAT3 signaling pathway has been considered as a valid target for anti-cancer drugs." (PMID 26010889, 2015). "STAT3 and NF-κB are two important transcription factors; both function as critical regulators in inflammation and cancer development, with vital roles to control the communication between cancer cells and inflammatory cells." (PMID 26631279, 2015). "As shown by this study, TLR9/NF-κB/STAT3 signaling coordinates expression of genes related to differentiation and renewal of normal or cancer stem cells." (PMID 26046794, 2015). "We showed that genetic targeting of TRiC in HS-578T and HEPG2 cancer cell lines, known to have constitutive STAT3 activation, resulted in significant reduction of STAT3 phosphorylation." (PMID 26561808, 2015).
cancer (continued). "As such, withaferin A induces apoptosis in a number of cell types putatively via down regulation of JAK/STAT3 in cancer cells." (PMID 26667305, 2015). "STAT3 is an oncogene that is hyper-activated in many cancers, including HNSCC, where STAT3 hyper-activation is associated with decreased survival and emergent resistance to EGFR-targeted therapy." (PMID 26267899, 2015). "Recently, it was reported that STAT family proteins, especially STAT3 play a crucial role in the initiation of various cancer transformation and progression." (PMID 25883212, 2015). "Autocrine and paracrine feed forward loops formed by cytokine-STAT3 signaling are recurrent themes in many human cancers." (PMID 26501341, 2015). "Among all the reported non-peptidomimetic small inhibitors, 5-hydroxy-9,10-dioxo-9,10-dihydroanthracene-1-sulfonamide (LLL12) has the lowest IC50 (0.16−3.09 μM), inhibiting STAT3 phosphorylation and the growth of human cancer cells." (PMID 25710482, 2015). "Recent studies have indicated that miRNAs are critical regulators of STAT3 signaling in the pathogenesis of cancer." (PMID 26631279, 2015). "The data obtained from other cancer systems reveal that resveratrol can inhibit the signaling pathways mediated by STAT3, Wnt and Notch when exerting its cancer suppressive effects." (PMID 25896424, 2015). "Many cancer cell lines show nuclear STAT3 translocation with subsequent transcriptional activation of programs such as the EMT." (PMID 26512918, 2015). "After trastuzumab treatment, both AKT and ERK phosphorylation were less downregulated while Jak1 and STAT3 phosphorylation were unregulated more obviously in EGFRvIII+HER2+ than in EGFRvIII−HER2+ cancer cell lines." (PMID 26474285, 2015). "Disruption of e.g. STAT3 dimer formation therefore provides an effective therapeutic approach in cancer by blocking its aberrant signaling hyperactivity and pro-oncogenic effects." (PMID 25710482, 2015). "For instance, small-molecule inhibitors of GPCR, TLR, and miRNAs related to STAT3 regulation can be applied to treat cancer." (PMID 26631279, 2015). "Another small molecule, stattic, was discovered by high-throughput screening and has been shown to selectively inhibit activation, dimerization, nuclear translocation of STAT3, and to increase apoptosis in STAT3-dependent cancer cell lines." (PMID 25710482, 2015). "Aside from their action on the actin cytoskeleton and Jak/STAT3 signaling, cucurbitacins have recently been shown to inhibit the mTORC1 activity in cancer cells." (PMID 25970614, 2015). "In this report, we further demonstrated that δ-T3 inhibited STAT3 signaling pathway, which plays a critical role in cancer cell proliferation and survival." (PMID 25849286, 2015). "We observed that both metformin and aspirin significantly inhibited the activity of STAT3, and STAT3 was previously showed to regulate Mcl-1 and Bcl-2 in various cancer cell lines." (PMID 26056043, 2015). "Basing on these findings, we suppose that the direct binding of Anxa2 to STAT3 facilitates STAT3 activation in cancer cells." (PMID 26307676, 2015). "In conclusion, our data identify anti-IGF-1R monoclonal antibody-induced cancer–stromal cell communication via STAT3-dependent IGF-2 production in cancer cells and a positive IGF-2/CXCL8 feedback loop through the intercellular IGF-2/IGF-2R system." (PMID 26465273, 2015). "STAT3 also plays a very critical role in metabolic reprogramming of cancer cells by driving metabolism towards aerobic glycolysis by transcriptional modulation." (PMID 26510913, 2015). "Recent study showed that IL-32 can affect the signaling of NF-κB and STAT3, which are confirmed to be the antiapoptotic and pro-angiogenic genes in cancer development." (PMID 25889282, 2015).
cancer (continued). "A key concept of the cancer-related inflammation pathway is that some genetic events endow cancer cells with growth advantages, among of which, an important one is the signal transducer and activator of transcription-3 (STAT3) signaling pathway." (PMID 25928665, 2015). "The STAT3 pathway is activated in many cancer types and is related with oncogenic transformation, angiogenesis, invasion, and metastasis and immune system suppression." (PMID 26542452, 2015). "Another significant result in this study is that Lycorine reverses EMT through STAT3 mediated Twist decrease, thus exhibits a novel mechanism that Lycorine inhibits cancer metastasis." (PMID 25915156, 2015). "STAT3-mediated expression of multidrug transporter MDR1 has been shown to facilitate resistance to chemotherapy in cancer cells." (PMID 25650658, 2015). "Due to their role in cell survival, proliferation and angiogenesis, STAT proteins, in particular STAT3 and STAT5, also have been implicated in cancer initiation and progression." (PMID 26272737, 2015). "The activation of STAT3 has been shown to protect cancer cells from apoptotic stimuli emanating from the Fas receptor." (PMID 25992623, 2015). "Other pathways linked to aggressive cancer include increased calcium signaling (NES = 2.03, FDR = 0.003), and increased Jak-Stat, Stat3, and NOTCH signaling in metastases." (PMID 24732363, 2014). "Several reports showed that inhibition of STAT3 suppressed the growth of cancer cells and enhanced the sensitivity to anticancer agents in multiple types of cancer." (PMID 24675568, 2014). "STA3 plays a role in the cancer development and progression and overexpression or high level of STAT3 has been observed in various types of cancers." (PMID 25295272, 2014). "STAT3, a tightly regulated transcription factor, is activated upon phosphorylation in response to IL-6 and has been shown to be present in a number of cancers." (PMID 25460165, 2014). "The ability of STAT3 to orchestrate a diverse set of immunosuppressive instructions has made it an attractive target for cancer vaccines." (PMID 24806510, 2014). "This study is the first of its kind to establish the involvement of RhoC in STAT3 phosphorylation and hence in promoting the activation of core cancer stem cells (CSCs) transcription factors." (PMID 24533098, 2014). "AG490 is a well-known JAK2 inhibitor which is able to effectively block STAT3 activation in different cancer cell lines." (PMID 24520293, 2014). "Aberrant STAT3 enhances uncontrolled growth and survival of cancer cells through dysregulation of gene expression, including cyclin D1, c-Myc, and survivin genes, and hence, contributing to tumorigenesis." (PMID 25365510, 2014). "Inhibiting IL-6/JAK/STAT3 signaling or STAT3 activity alone with antisense oligonucleotides, siRNA, or small-molecule inhibitors can dramatically sensitize cancer cells to treatment with EGFR inhibitors." (PMID 24662938, 2014). "Taken together, these results clearly showed that STAT3 plays a critical role in conferring anoikis resistance and promoting cell migration in cancer cells." (PMID 25216522, 2014). "The downregulation of these proteins suggests the profound antitumor potential of HO-3867 by inhibition of STAT3 activation and its target proteins, even in hypoxic cancer cells." (PMID 25594014, 2014). "Nevertheless, most STAT3 inhibitors have yet to be translated to clinical evaluation for cancer treatment, presumably because of pharmacokinetic, efficacy, and safety issues." (PMID 24662938, 2014). "STAT3 is an essential factor in oncogenic cellular transformation, since it is frequently and persistently activated in various types of cancers and constitutive activation of STAT3 is sufficient to convert normal cells into cancer cells." (PMID 24743778, 2014).
cancer (continued). "Inappropriate activation of STAT3 has been revealed in various types of solid and hematological cancers, and blocking the STAT3 signaling pathway by various means is effective in killing cancer cells in many experimental models." (PMID 24995504, 2014). "In this review, we summarize current literature and discuss the potential importance of STAT3 as a novel target for cancer prevention and of STAT3 inhibitors as effective chemopreventive agents." (PMID 24743778, 2014). "We also show that cancer stem cell promoting activity can be blocked by inhibition of the STAT3 signaling pathway." (PMID 24652403, 2014). "In our previous study, SC-2001 was identified to be SHP-1 agonist, and a negative regulator of STAT3 (which is over-expressed in various cancers), by enhancing SHP-1 expression via transcription activity." (PMID 24952874, 2014). "KEGG analysis showed that the STAT3-mediated novel miRNAs influence the cancer-related signaling pathway significantly, including ErbB signaling pathway, MAPK signaling pathway, and Notch signaling pathway (adjusted P < 0.05, Bonferroni correction)." (PMID 25126546, 2014). "To delineate STAT3‐induced metabolic alterations from Gln driven metabolic pathways in high‐invasive cancer cells, we used AG490 to measure glycolytic and OXPHOS activity in OVCA cells." (PMID 24799285, 2014). "Suppression of STAT3 activity by small-molecule inhibitors leads to increased apoptosis, chemosensitivity, and decreased angiogenesis in cancer cells with constitutively activated STAT3." (PMID 25327561, 2014). "We believe that this new knowledge carries significant implications in how we should evaluate the prognostic value of STAT3 in tumors, and in how we design new anti-cancer drugs targeted against STAT3." (PMID 24995504, 2014). "Constitutive activation of STAT3 in cancer cells also can be attributed to the expression of various oncogenic protein tyrosine kinases (PTKs)." (PMID 24995504, 2014). "Activation of STAT3 has been described in nearly 70% of solid and hematological tumors, emphasizing the importance of STAT3 as a direct target in cancer therapy." (PMID 25149535, 2014). "For the constitutive activation of STAT3 to occur, as is seen in cancer, there needs to be activation of some upstream process driving the activity of a kinase that can phosphorylate Tyr-705 of STAT3." (PMID 24762632, 2014). "Levels, folding, and function of the infamous cancer and inflammatory disease-related signaling molecule Stat3 are regulated by interaction with the chaperonin TRiC; manipulation of this interaction is a therapeutic avenue for exploration." (PMID 24756126, 2014). "The involvement of the JAK-STATs signaling pathway in IL-6/IL-6R signaling and involvement of STAT3 phosphorylation in EMT of cancer cells has been proved by lots of results." (PMID 24789104, 2014). "One of these compounds, designated as HO-3867, displays selective cytotoxicity to cancer cells and has shown promise as a potential anticancer drug through the targeting STAT3." (PMID 25594014, 2014). "The EGFR signaling pathway, including its multiple downstream pathways, such as PI3K/AKT, ERK1/2, JAK/STAT3 and mTOR/NF-κB, plays an important role in the regulation of proliferation, survival, migration and chemoresistance in cancer cells." (PMID 24586249, 2014). "SOCS1, another member of the SOCS family, is also frequently silenced by gene methylation, and this biochemical aberrancy has been shown to contribute to constitutive STAT3 activation in a wide range of cancer types." (PMID 24995504, 2014). "It is well accepted that STAT3 can directly activate miR-21, one of the miRNAs that promote cancer cell survival and proliferation." (PMID 25126546, 2014). "Increased evidences show that STAT3 is an important and often essential factor in oncogenic cellular transformation and in cancer." (PMID 25476455, 2014).